CTLA4 (cytotoxic T-lymphocyte associated protein 4)
Diseases named in the same sentence as CTLA4 in open-access papers (continued):
Sharing a sentence is not in itself a finding about the gene and the disease.
metastatic melanoma (continued). "The clinical revolution of using CPI to treat cancer started with the approval of CTLA4 antibody, ipilimumab, by the United States Food and Drugs Administration (FDA) to treat metastatic melanoma patients." (PMID 33076303, 2020). "For example, in patients with metastatic melanoma, the objective response rate (ORR) for ipilimumab (anti-CTLA-4) was about 10%–16% and for nivolumab (anti-PD-1) was 30%–40%." (PMID 31974523, 2020). "Ipilimumab (MDX-010) is a humanized antibody against CTLA-4, currently approved by the FDA for the treatment of metastatic melanoma, either alone or in combination with PD-1 inhibitors." (PMID 33036192, 2020). "The use of novel immunotherapies, especially immune checkpoint inhibitors including CTLA-4, PD-1 and others, as well as targeted BRAF and MEK inhibitors have significantly improved outcomes for many patients with metastatic melanoma." (PMID 32894202, 2020). "Only one phase I/II clinical study has been investigated administrating anti-CTLA4 antibody with anti-CD40 agonist (CD40; M1-TAMs marker) in metastatic melanoma." (PMID 32756500, 2020). "Articles were included if they examined the treatment of intracranial metastatic melanoma with SRS and BRAFi/MEKi inhibitors or immunotherapeutic checkpoint inhibitors (i.e., anti-PD1 and anti-CTLA4 monoclonal antibodies)." (PMID 31886081, 2019). "The human anti-CTLA-4 antibody ipilimumab was demonstrated to be effective in a phase III clinical trial and received FDA approval for treating metastatic melanoma in 2011." (PMID 31028434, 2019). "We present the case of a 67 year old Caucasian male that was initially treated with BRAF inhibitors followed by anti-CTLA4 and then anti-PD1 immunotherapy for metastatic melanoma but later developed colorectal cancer." (PMID 31727009, 2019). "One CTLA-4 antibody, ipilimumab, has been shown in multiple phase II/III trials to be an effective therapeutic option in the treatment of metastatic melanoma." (PMID 28430133, 2017). "Lpilimumab, a monoclonal antibody directed to the immune checkpoint receptor termed “cytotoxic T lymphocyte antgen-4 (CTLA-4)”, received FDA approval for treatment of metastatic melanoma in March 2011." (PMID 29069859, 2017). "Despite concerns about uncontrollable autoimmunity resulting from systemic CTLA-4 blockade, ipilimumab, a monoclonal antibody against CTLA-4, improved overall survival in patients with metastatic melanoma." (PMID 27959922, 2016). "LMD remains a devastating complication of cancer despite the significant improvement in overall survival of patients with metastatic melanoma with new effective systemic treatments, including selective BRAF inhibitors and anti-CTLA-4 antibody." (PMID 25962795, 2015). "Cytokines under investigation for the treatment of metastatic melanoma include IL-21, which produced an ORR of 22.5%, and is tested both alone and in phase I trials in combination with anti-CTLA4 (NCT01489059) and anti-PD1 antibody (NCT01629758)." (PMID 24743024, 2014). "Ipilimumab targets the T cell inhibitory molecule CTLA-4, which is highly expressed by Treg, and is FDA-approved for treatment of metastatic melanoma." (PMID 24302925, 2013). "The blocking of the physiological inhibitory function of CTLA-4 in T cells is the rationale for the employment of antagonistic anti-CTLA-4 mAbs as therapeutic tools to treat different solid tumors, mainly metastatic melanoma." (PMID 23634660, 2013). "Recently, immune checkpoint inhibitors, including the anti-CTLA-4 monoclonal antibody ipilimumab and the anti-PD monoclonal antibody MDX-1106, have shown single agent efficacy in patients with metastatic melanoma." (PMID 22175026, 2011). "In patients with metastatic melanoma resistant to anti-PD-L1 monotherapy, combination of anti-CTLA4 plus anti-PD-1 resulted in a median 3·0 months progression-free survival (PFS) compared to anti-CTLA4 alone with 2·6 months PFS." (PMID 40760097, 2025).
metastatic melanoma (continued). "Anti-CTLA-4 agents were the first ICIs that were considered effective for cancer treatment, and ipilimumab was the first approved anti-CTLA-4 monoclonal antibody (mAb) for metastatic melanoma." (PMID 40564107, 2025). "In this study, using the Elastic Net Regression (ENLR) algorithm, we built an immunometabolism signature using on-treatment (IMME-ON) tumor specimens based on clinical information and transcriptome data from patients with metastatic melanoma after anti-PD1 and or anti-CTLA4 treatment." (PMID 40591071, 2025). "The same group also reported a case of a normozoospermic 30-year-old patient treated for BRAF-negative stage IV metastatic melanoma, who developed azoospermia (Sertoli cell-only syndrome) two years after combined treatment with anti-PD1 and anti-CTLA4 (ipilimumab/nivolumab)." (PMID 38539511, 2024). "This compares to an mPFS of 16.8 m (anti-PD-1/CTLA-4), 5.6 m (anti-PD-1), and 3.4 m (anti-CTLA-4) in CHECKMATE-067, and 11.6 m (Anti-PD-1) in KEYNOTE 006, both trials of ICIs in metastatic melanoma, with a pre-specified stratification for patients with BRAF mutations." (PMID 38339280, 2024). "To confirm these results, we analyzed a publicly available CyTOF dataset and found that CTLA-4 protein levels were reduced in circulating immune cells (CD45+), CD4+ T cells, and Treg cells (CD4+CD25+CD127-) in metastatic melanoma patients compared to healthy donors." (PMID 37197667, 2023). "have shown that the scope of antigen reactivity can be broadened by anti-CTLA-4 treatment but not anti-PD-1 treatment, in the case of metastatic melanoma." (PMID 37359554, 2023). "The emergence of new therapies such as immune checkpoint inhibitors (ICI), represented by anti-PD1 and anti-CTLA4, have improved the overall survival (OS) and progression-free survival (PFS) of patients with advanced and metastatic melanoma and are now validated for their therapeutic management." (PMID 35804963, 2022). "The most successful treatment options against non-resettable metastatic melanoma are immunotherapies with antibodies directed against CTLA-4 and PD-1 or their combination (small kinase and checkpoint inhibitors)." (PMID 35208960, 2022). "In the metastatic melanoma cohort, responders to anti-CTLA4 possessed a higher NRGscore than non-responders." (PMID 35875102, 2022). "Thus, this fixed-dose combination trial laid the foundation for dual inhibition apart from anti-CTLA4/anti-PD-1 pathways for clinical use and was recently FDA approved for patients with unresectable or metastatic melanoma." (PMID 36159789, 2022). "Recent studies suggest that patients with metastatic melanoma who progress on PD-L1-directed therapy can respond to combined PD-L1 and CTLA-4 inhibition, but it is still not clear the clinical impact of this combination in terms of safety." (PMID 35625837, 2022). "recently reported results of a multi-centre retrospective study of 835 patients with metastatic melanoma receiving anti-CTLA-4 or anti-PD-1 therapy with or without previous radiotherapy for unresectable metastases." (PMID 34733287, 2021). "CTLA-4 is an immune checkpoint molecule that downregulates pathways of T cell activation, and “Ipilimumab” can inhibit CTLA-4 to improve survival in patients with metastatic melanoma." (PMID 33680968, 2021). "However, the course of metastatic melanoma treatment has changed markedly since the introduction of the immune checkpoint inhibitors designed against either cytotoxic T-lymphocyte-associated antigen 4 (CTLA-4) or Programmed death receptor-1 (PD-1), both negative regulators of T-cell immune function." (PMID 34830947, 2021). "While immune checkpoint inhibitors targeting the CTLA-4 and PD-1 receptors have significantly improved outcomes of many patients with metastatic melanoma, there remains a group of patients who demonstrate no benefit." (PMID 34202352, 2021).
metastatic melanoma (continued). "Moreover, therapy with immune checkpoint blockade, i.e., ipilimumab (anti-CTLA4), nivolumab and pembrolizumab (anti-PD1), has been established as the standard-of-care for malignant metastatic melanoma." (PMID 33520112, 2021). "In contrast to metastatic melanoma, the role of single-agent anti-CTLA-4 therapy is not well defined in metastatic renal cell carcinoma (mRCC)." (PMID 34737281, 2021). "It has been indicated that anti-CTLA-4 administration can potentiate the immune responses of NY-ESO-1 antigen-specific B cell and T cells through augmented production of MIP-1β, IFN-γ, and TNF-α in patients suffering from metastatic melanoma." (PMID 32902664, 2021). "Forty patients with metastatic melanoma who did not respond to anti-PD-1 +/− anti-CTLA-4 treatment were identified." (PMID 34202352, 2021). "In metastatic melanoma treated with CTLA-4 blockers, responders and non-responders to ICI had a differential DNA methylation pattern." (PMID 34858994, 2021). "The anti-CTLA-4 monoclonal antibody ipilimumab has been confirmed to have efficacy in treating multiple types of advanced tumors, such as gastric cancer, non-small cell lung cancer (NSCLC), metastatic melanoma, and urologic neoplasms." (PMID 32983168, 2020). "CTLA-4, present on the surface of cluster differentiation (CD) 4+ and CD8+ lymphocytes, is another important pharmacological target for the treatment of several neoplastic forms, including metastatic melanoma." (PMID 33036192, 2020). "In metastatic malignant melanoma (MM), anti-PD1 therapy has been proven as superior treatment to chemotherapy as first-line therapy and after ipilimumab (anti-CTLA-4 antibody) failure and in non-small cell lung cancer (NSCLC) patients after progression to first-line chemotherapy." (PMID 31156434, 2019). "In addition to anti-CTLA-4 antibodies, several anti-PD-1/PD-L1 antibodies were tested in combination with BRAF/MEK inhibitors in metastatic melanoma (NCT01656642, NCT02130466, and NCT02818023)." (PMID 31134073, 2019). "Clinically, ipilimumab, a humanized CTLA-4 antibody and the first FDA-approved immune checkpoint inhibitor, has been demonstrated to improve OS in a phase III clinical trial for metastatic melanoma patients, however, with only a complete response observed in 2% patients." (PMID 28299344, 2017). "Even the CTLA-4 inhibitor ipilimumab that has successfully been used in the clinic for treatment of metastatic melanoma did not enhance proliferation in our setting when used as a single agent." (PMID 28588576, 2017). "CTLA-4 is one of the first immune checkpoints to be clinically targeted in cancer therapy and Ipilimumab (Bristol–Myers Squibb, New York, NY, USA), a monoclonal CTLA-4 antibody, was approved by FDA in 2011 for the treatment of metastatic melanoma." (PMID 29135922, 2017). "Metastatic melanoma remains a fatal disease to many worldwide, even after the breakthrough introduction of targeted therapies such as BRAF inhibitors and immune checkpoint blockade therapies such as CTLA-4 and PD-1 inhibitors." (PMID 28435677, 2017). "We report a 63-year-old man with metastatic melanoma successfully treated with combination CTLA-4 and PD-1 blockade (ipilimumab and nivolumab), after non-response to pembrolizumab monotherapy." (PMID 27660712, 2016). "CTLA4 negatively regulates T-lymphocyte proliferation and activation, and inhibitors of this molecule are approved by the Food and Drug Administration (FDA) as a treatment for metastatic melanoma." (PMID 27165193, 2016). "Several agents, including interferon-alpha, high-dose interleukin-2 (IL-2), and checkpoint inhibitors targeting the cytotoxic T lymphocyte antigen 4 (CTLA-4) and programmed cell death 1 (PD-1) receptors have been approved by the FDA for the treatment of metastatic melanoma." (PMID 25992289, 2015).
metastatic melanoma (continued). "The resurgence of interest in immunotherapeutic methods (e.g. IL-2, CTLA4, PD-1, PDL-1) for the treatment of metastatic melanoma and cancer in general, opens new approaches to therapeutic design through the better understanding of modulation of the immune system." (PMID 27437102, 2014). "In monitoring MDSC in metastatic melanoma patients treated with the combination of tremelimumab/HDI, we first reported a significant regulatory impact on these cellular mediators of immunosuppression in a trial involving CTLA-4 blockade." (PMID 24498358, 2014). "Ipilimumab has been shown to enhance pre-exisiting immune responses, including antitumor responses, by directly blocking cytotoxic T-lymphocyte antigen-4 (CTLA-4) mediated T cell inhibition and is now FDA and EMA approved as treatment modality in patients with metastatic melanoma." (PMID 23341990, 2013). "The anti-CTLA-4 monoclonal antibody ipilimumab is being tested in combination with an IDO inhibitor and also with nivolumab in a phase III trial in patients with previously untreated metastatic melanoma." (PMID 24829752, 2013). "Two recent immune strategies that obtained FDA approval include vaccination against sipuleucel-T for metastatic CaP, and antibody-mediated blockade of the T-cell negative co-stimulatory receptor CTLA-4 for the treatment of metastatic melanoma." (PMID 22493742, 2012). "Although single-agent immune checkpoint inhibitor (ICI) therapy with monoclonal antibodies targeting CTLA-4 and PD-1 has been the standard of care for patients with metastatic melanoma, the majority of patients did not experience long-term benefits from ICI monotherapy." (PMID 40507314, 2025). "This study recruited patients with unresectable or metastatic melanoma who have not previously received therapy for unresectable or metastatic disease, as well as those who have not received therapy with anti-CTLA4 and/or anti–PD-1/PD-L1/PD-L2 or targeted therapies." (PMID 39296979, 2024). "Monoclonal antibodies against CTLA-4 or PD-1 or PDL-1 are the most studied ICIs in randomized clinical trials, however, more recently, an anti-LAG3 (Lymphocyte activation gene-3) antibody, Relatlimab, has been approved by FDA in combination with Nivolumab for metastatic melanoma therapy." (PMID 38322766, 2024). "Patients diagnosed with metastatic melanoma with no previous medical intervention are administered a combination treatment consisting of relatlimab+nivolumab and nivolumab+ipilimumab, which involves the use of an anti-CTLA-4 monoclonal antibody." (PMID 38390331, 2024). "The first checkpoint inhibitor against cytotoxic T lymphocyte protein 4 (CTLA-4, CD152, ipilimumab; Bristol-Myers Squibb; interacts with CD80 (B7.1), alternatively with CD86 (B7.2)) has been approved in March 2011 in the US for the treatment of patients with unresectable or metastatic melanoma." (PMID 37174080, 2023). "When metastatic melanoma patients on CTLA-4 blockade and PD-1 blockade were ranked by the normalized expression of each of these genes, the sum of these ranks was an excellent predictor (area under ROC curve >0.95) of eventual response to CTLA-4 blockade and PD-1 blockade respectively." (PMID 35309122, 2022). "In addition, given the small number of patients, we have carried out external validation with eight external cohorts of metastatic melanoma patients, six treated with anti-PD1, one treated with anti-PD1 + anti-CTLA4 and one treated with anti-CTLA4 in the context of five different studies." (PMID 36012390, 2022). "To date, the cocktail of nivolumab (anti-PD1 antibody) and ipilimumab (anti-CTLA-4 antibody) was the first approved and remains the only anti-ICM antibody combination approved in the clinic as first-line treatment for untreated patients with metastatic melanoma." (PMID 34572847, 2021).
metastatic melanoma (continued). "As follows, the non-depleting, anti-CTLA-4 Ab Tremelimumab (but not the depleting Ab Ipilimumab) showed limited activity in metastatic melanoma and breast cancer;24,53,54 what could be explained by its low capacity to deplete CTLA-4-expressing Tregs." (PMID 32601304, 2020). "Furthermore, metabolomics analysis has recently identified significant differences in 83 gut metabolites at baseline in responders to anti-PD-1 and anti-CTLA-4 therapy compared to nonresponders with metastatic melanoma." (PMID 30887236, 2019). "Similarly, loss of function mutations in APLNR gene was identified in non-responding tumor lesions of metastatic melanoma and lung cancer patients treated with anti-PD-1 or anti-CTLA-4 therapy." (PMID 29968076, 2018). "In this context, metastatic melanoma may induce chronic high level of IL6, which can both confer aggressiveness and compromise the immune-inflammatory regulation, impairing the immune response elicited by CTLA4 blockade." (PMID 29642948, 2018). "In a phase II trial of systemic administration of recombinant GM-CSF (sargramostim) plus ipilimumab in metastatic melanoma patients, their 1-year survival increased upon combination therapy compared with anti-CTLA-4 alone (68.9 versus 52.9%) without toxicity differences." (PMID 27847783, 2016). "Aided by this technique, in the current work we explored the effects of the anti-CTLA4 antibody tremelimumab on the phosphorylated state of key effectors of the TCR and cytokine signaling pathways within immune subsets of cells obtained from peripheral blood of patients with metastatic melanoma." (PMID 20856802, 2010). "Indeed, a past study confirmed that IFIT2 is significantly up-expressed in patients who are not sensitive to anti-CTLA-4 therapy in metastatic melanoma, suggesting that the IFIT family may be useful for predicting the efficacy of immune checkpoint therapy." (PMID 37980495, 2023). "However, their clinical utility remains controversial, and to the best of our knowledge, only one study applied the imPERCIST5 criteria to a series of patients treated with ipilimumab, and none in patients on first-line antiPD1 (or anti PD1/anti CTLA4 combination) for advanced/metastatic melanoma." (PMID 35804963, 2022). "The safety and efficacy of CTLA-4 blockade with ipilimumab has been evaluated in a number of phase I, II, and III trials demonstrating that therapy with ipilimumab may result in a significant improvement in OS for a selected group of patients with metastatic melanoma." (PMID 25619164, 2015). "A total of 21 non-surgical metastatic melanoma patients treated with ICI were involved in the study, including anti-PD-1 monotherapy or a combination of anti-PD-1 and anti-CTLA-4 therapy." (PMID 40563673, 2025). "RNA-seq profiling of plasma EVs isolated from metastatic melanoma patients showed a decrease in several transcripts and pathways related to CD28 costimulatory, T-cell receptor, and CTLA4 signaling during treatment with ICIs in non-responders." (PMID 39336143, 2024). "Immunotherapy, targeting specific immune checkpoints including cytotoxic T-lymphocyte antigen 4 (CTLA-4), programmed cell death 1 (PD1), and programmed cell death ligand 1 (PD-L1) has revolutionized the treatment of both locally advanced and metastatic melanoma and non-melanoma skin cancer." (PMID 34291066, 2021). "For decades no new therapeutic agent has been approved for metastatic melanoma by the FDA until a recent study, which showed survival benefit of a monoclonal antibody targeting a regulatory checkpoint, CTLA-4, in T-cells and led to the approval of ipilimumab in 2011." (PMID 26460952, 2015).
metastatic melanoma (continued). "While CTLA4 expression was not significantly different in CD14+, CD15+, and CD56+ cells between the two groups, the levels were significantly downregulated by approximately 30% in both CD3+ and CD19+ cells from metastatic melanoma patients compared to healthy donors." (PMID 37197667, 2023). "Moreover, some patients with metastatic melanoma with the gut microbiota defined as cluster B, which was not significantly responsive to anti‐CTLA‐4, were converted to cluster C, which was considerably responsive, after receiving anti‐CTLA‐4 antibodies treatment." (PMID 38082435, 2023).